WDCP (WD repeat and coiled coil containing)
Synonyms: C2orf44; PP384; FLJ21945; MMAP
Tractability: PROTAC: ubiquitination databases record sites on it.
Gene: Protein-coding gene on chromosome 2 (24,029,347 to 24,049,575, reverse strand). Ensembl gene ENSG00000163026.
Subcellular location (Human Protein Atlas): Nucleoli; Cytosol
Pathways (Reactome):
Disease: Signaling by ALK fusions and activated point mutants
Gene Ontology:
Molecular function: kinase binding
Biological process: protein complex oligomerization
Genetic constraint (gnomAD): Loss-of-function variants: 19 observed, 39.48 expected, observed/expected ratio (o/e) 0.48, 90% interval 0.34 to 0.71. The upper end of that interval is the gene's LOEUF score, 0.71, which puts it in group 2 of 6, group 1 being the genes least tolerant of losing a copy. Missense variants: 771 observed, 864.24 expected, observed/expected ratio (o/e) 0.89, 90% interval 0.84 to 0.95. Synonymous variants: 290 observed, 328.68 expected, observed/expected ratio (o/e) 0.88, 90% interval 0.8 to 0.97.
Homologues: Orthologues: chimpanzee WDCP (99% identical), macaque WDCP (95% identical), dog WDCP (70% identical), pig WDCP (69% identical), mouse Wdcp (63% identical), rabbit WDCP (63% identical), guinea pig WDCP (61% identical), rat Wdcp (59% identical), tropical clawed frog wdcp (49% identical), zebrafish wdcp (45% identical), tropical clawed frog wdcp.2 (38% identical).
Diseases named in the same sentence as WDCP in open-access papers:
WDCP is named in the same sentence as 2 diseases in open-access papers, as found by Europe PMC text mining. Sharing a sentence is not in itself a finding about the gene and the disease.
WDCP shares sentences with these, for which no sentence is quoted: cancer (1 paper); tumor (1).